PDCD2 (programmed cell death 2)
Description:
Chaperone for ribosomal protein uS5; cotranslationally associates with uS5 and accompanies the ribosomal protein to assembly sites in the nucleus; appears to function redundantly to PDCD2L.
Synonyms: RP8; ZMYND7
Tractability: PROTAC: UniProt records ubiquitination sites on it; ubiquitination databases record sites on it; its protein half-life has been measured.
Gene: Protein-coding gene on chromosome 6 (170,575,295 to 170,584,692, reverse strand). Ensembl gene ENSG00000071994.
Subcellular location: Nucleus, nucleolus; Cytoplasm, cytosol
Subcellular location (Human Protein Atlas): Nucleoplasm; Cytokinetic bridge
Gene Ontology:
Molecular function: enzyme binding; protein binding; protein carrier chaperone
Biological process: regulation of hematopoietic progenitor cell differentiation; ribosomal small subunit biogenesis
Cellular component: cytosol; extracellular exosome; nucleolus; nucleus; cytoplasm
Genetic constraint (gnomAD): Loss-of-function variants: 31 observed, 23.75 expected, observed/expected ratio (o/e) 1.31, 90% interval 0.98 to 1.74. The synonymous counts are far from expectation, so gnomAD's model fits this gene poorly and the ratio says little. Missense variants: 392 observed, 294.57 expected, observed/expected ratio (o/e) 1.33, 90% interval 1.22 to 1.45. Synonymous variants: 181 observed, 118.59 expected, observed/expected ratio (o/e) 1.53, 90% interval 1.35 to 1.73.
Homologues: Orthologues: macaque PDCD2 (97% identical), chimpanzee PDCD2 (96% identical), mouse Pdcd2 (85% identical), rabbit PDCD2 (85% identical), rat Pdcd2 (83% identical), dog PDCD2 (73% identical), tropical clawed frog pdcd2 (59% identical), zebrafish pdcd2 (49% identical), Drosophila melanogaster Zfrp8 (40% identical), Caenorhabditis elegans pdcd-2 (39% identical). Paralogues in human: PDCD2L (27% identical), ZMYND12 (11% identical).
Diseases named in the same sentence as PDCD2 in open-access papers:
PDCD2 is named in the same sentence as 41 diseases in open-access papers, as found by Europe PMC text mining. Sharing a sentence is not in itself a finding about the gene and the disease. The quoted sentences say what the papers report.
gastric cancer (4 papers, 2019 to 2024). A primary or metastatic malignant neoplasm involving the stomach. "APOBEC3B downregulation with shRNA resulted in enhanced cytotoxicity of PDCD2 (programmed cell death protein 2) in gastric cancer cell line MKN28, probably due to the lower mutational load and noninterfered transcription of this tumour suppressor gene." (PMID 37568604, 2023). "Plus, loss of PDCD2 expression could induce gastric cancer development and progression through cell growth arrest at the early S phase of the cell cycle and reported as a putative tumor suppressor in gastric stromal tumors." (PMID 31244774, 2019). "Aberrant expression of PDCD2 is associated with many tumors, such as leukemia and gastric cancer." (PMID 31244774, 2019). "PDCD2 expresses at a low level in osteosarcoma and gastric cancer, and the knockdown of PDCD2 promotes cancer cell proliferation." (PMID 34608122, 2021).
lymphoma (4 papers, 2012 to 2024). A malignant (clonal) proliferation of B- lymphocytes or T- lymphocytes which involves the lymph nodes, bone marrow and/or extranodal sites. "Homo sapiens programmed cell death 2 (PDCD2), transcript variant 1, mRNA promotes apoptosis in several human lymphomas." (PMID 22690114, 2012). "The involvement of PDCD2 in the development of lymphomas in human B and T cells has been shown." (PMID 39022129, 2024). "Moreover, BCL6 has a negative correlation with caspase-3 level in glioma tissues and it targeting PDCD2 to activate the caspase cascade results in the inhibition of apoptosis in lymphomas." (PMID 30420967, 2018). "Increased PDCD2 expression can induce apoptosis in human cells, at least in part by activating a caspase cascade, whereas repression of PDCD2 is involved in the pathogenesis of certain human lymphomas." (PMID 23468121, 2013).
acute leukemia (3 papers, 2019 to 2024). A clonal (malignant) hematopoietic disorder with an acute onset, affecting the bone marrow and the peripheral blood. "However, PDCD2 is highly expressed in human acute leukemia cells and PDCD2 overexpression facilitates cancer cell growth." (PMID 34608122, 2021). "PDCD2 is an important predictor of clinical relapse in acute leukemia patients." (PMID 31244774, 2019).
glioma (3 papers, 2018 to 2024). A benign or malignant brain and spinal cord tumor that arises from glial cells (astrocytes, oligodendrocytes, ependymal cells). "PDCD2 was also evaluated on glioma (GBMLGG) cells using the CCK8, colony formation, transwell assays, and xenograft tumor model." (PMID 39022129, 2024). "Functional enrichment analysis, CCK8, colony formation assay, transwell assay, and xenograft tumor model were undertaken to study the PDCD2's biological function in glioma (GBMLGG)." (PMID 39022129, 2024). "By conducting Pearson correlation analysis on glioma samples from the CGGA and TCGA databases, it was discovered that the expression of SOCS1 is significantly positively correlated with several known inhibitory immune checkpoints, including HVEM, TIM-3, PD-1, PDCD2, TIGIT, CD200R1, CTLA4, and CD47." (PMID 39654174, 2024).
leukemia (3 papers, 2010 to 2024). A malignant (clonal) hematologic disorder, involving hematopoietic stem cells and characterized by the presence of primitive or atypical myeloid or lymphoid cells in the bone marrow and the blood. "In the past, we showed that ART induced apoptosis in KG-1a leukemia cells, and that a number of apoptosis-regulating genes (LOC51272, CIDEB, PDCD2, BAG1, BAG3, MADD) correlated with cellular responses towards ART." (PMID 20428086, 2010).
gastrointestinal stromal tumor (2 papers, 2024). "Also, increased expression of Programmed cell death 2 (PDCD2) maintains gut barrier cells and limits the formation of gastrointestinal stromal tumors." (PMID 39457699, 2024).
lung carcinoma (2 papers, 2014 to 2022). "Among members of the ZMYND family, programmed cell death 2 (PDCD2)/ZMYND7, ubiquitin specific protease 19(USP19)/ZMYND9, and beta catenin in lung cancer (BLU)/ZMYND10 only contain MYND motif in their respective carboxylterminus, with length between 30 and 40 amino acid residues." (PMID 36520265, 2022). "In previous studies, knockdown of PDCD2 in human lung cancer cells induced slowing of the cell cycle without an obvious specific defect." (PMID 25150276, 2014).
kidney chromophobe (1 paper, 2024). "In addition, low expression of PDCD2 in cancer was observed in kidney clear cell carcinoma (KIRC), kidney chromophobe (KICH), and thyroid carcinoma (THCA)." (PMID 39022129, 2024).
mammary tumor (1 paper, 2007). "Four other ESTs, two from mammary tumor (AW211687 and AW212179) and two from a forelimb of E13 embryo (CJ049248 and CR514396) were identified upstream of the 5' end of Pdcd2, suggesting there may be a new gene transcribed from the same promoter as Pdcd2, but in the opposite orientation." (PMID 17233890, 2007).
ocular melanoma (1 paper, 2024). A melanoma that arises from the structures of the eye or ocular adnexa. "The highest frequency of PDCD2 alterations (>6%) was observed in ocular melanoma." (PMID 39022129, 2024).
sarcoma (1 paper, 2024). A usually aggressive malignant neoplasm of the soft tissue or bone. "A higher level of PDCD2 expression was associated with lower overall survival (OS) for adrenocortical carcinoma (ACC), GBMLGG, LIHC, and Sarcoma (SARC), poor disease-specific survival (DSS) in ACC, GBMLGG, and UCEC, and poor progression-free interval (PFI) in ACC, GBMLGG, HNSC, LIHC, OV, and UCEC." (PMID 39022129, 2024).
cancer (8 papers, 2014 to 2026). A tumor composed of atypical neoplastic, often pleomorphic cells that invade other tissues. "– Encodes a highly conserved nuclear protein, – Abnormal PDCD2 expression alters cell apoptosis. – Alteration of PDCD2 expression could be conducive to human cancer development and progression." (PMID 31244774, 2019). "Using this biosensor, we identified an 11-amino acid uS5-derived peptide that inhibits the PDCD2-uS5 interaction and impairs cancer cell viability." (PMID 41933732, 2026). "The TCGA, CGGA, GEPIA, cBioPortal, and GTEx databases were analyzed for expression, prognostic value, and genetic modifications of PDCD2 in cancer patients." (PMID 39022129, 2024). "During this study, it was observed that PDCD2 expression levels were notably elevated in various forms of malignancies." (PMID 39022129, 2024). "Since PDCD2 expression was differently expressed in many types of cancer, the ability of prognostic values of PDCD2 in human cancer was explored." (PMID 39022129, 2024). "Despite having explored the relationship between PDCD2 and prognosis in pan-cancer, PDCD2 function has only been confirmed in GBMLGG, but further in vivo and in vitro studies are needed to elucidate its molecular mechanism in cancer development." (PMID 39022129, 2024). "Now, we have a better understanding of how PDCD2 plays a role in pan-cancer, but there are still some inconsistencies." (PMID 39022129, 2024). "As cancer cells require a substantial supply of ribosomes to maintain elevated levels of protein synthesis, targeting the protein interaction interface between PDCD2 and uS5 is a promising modality to mitigate ribosome biogenesis." (PMID 41933732, 2026). "Furthermore, we found that copy number variations (CNV) of PDCD2 regulate gene expression through different means (increasing or decreasing) in diverse cancer types." (PMID 39022129, 2024). "Programmed cell death 2 (PDCD2) is related to cancer progression and chemotherapy sensitivity." (PMID 39022129, 2024). "As a molecular predictor of cancer prognosis, PDCD2 can be used clinically to detect GBMLGG." (PMID 39022129, 2024). "At present, there have been no investigations conducted to determine if PDCD2 is linked to overall cancer prognosis." (PMID 39022129, 2024). "ROC curve analysis indicates that PDCD2 could serve as a highly specific and sensitive biomarker for the diagnosis of different types of cancers." (PMID 39022129, 2024). "Our findings indicate that PDCD2 could be used for cancer diagnosis and prognosis and as a molecular target for GBMLGG." (PMID 39022129, 2024). "In addition, the aberrant expression of PDCD2 is relevant to the development of cancer." (PMID 34608122, 2021). "However, growth inhibition was seen in the presence of small amounts of residual PDCD2 protein both in our Tam-treated ESCs, as well as in siRNA-mediated PDCD2 knockdown (but not complete knockout) in cancer cell lines." (PMID 25150276, 2014).
tumor (4 papers, 2019 to 2024). "According to these results, PDCD2 has different mutation forms in different tumor types." (PMID 39022129, 2024). "The tumor growth curve indicated that the growth rate of xenograft tumors created by U87 cells with reduced PDCD2 levels was noticeably decreased in comparison to the NC." (PMID 39022129, 2024). "Further, we examined the impact of PDCD2 on GBMLGG in an in vivo setting by utilizing a xenograft tumor model." (PMID 39022129, 2024). "Five genes at 6q27 exhibiting large genomic changes (PSMB1, PDCD2, TBP, OR4F7P and WBP1LP8) were found in HCI-010 as the region transitioned from amplified in the human tumor to deleted in the early passage of the PDX and PDxO." (PMID 35221336, 2022).
PDCD2 also shares sentences with these, for which no sentence is quoted: acute myeloid leukemia (1 paper); bladder urothelial carcinoma (1); cholangiocarcinoma (1); colon adenocarcinoma (1); digestive system tumors (1); esophageal adenocarcinoma (1); esophageal carcinoma (1); glioblastoma (1); head and neck squamous cell carcinoma (1); Huntington disease (1); kidney clear cell carcinoma (1); liver cancer (1); lung adenocarcinoma (1); lung squamous cell carcinoma (1); nervous system tumor (1); osteosarcoma (1); ovarian serous cystadenocarcinoma (1); pancreatic adenocarcinoma (1); periventricular nodular heterotopia (1); prostate adenocarcinoma (1); rectum adenocarcinoma (1); skin cutaneous melanoma (1); spinocerebellar ataxia (1); stomach adenocarcinoma (1); testicular germ cell tumor (1); thyroid carcinoma (1); uterine carcinosarcoma (1); uterine corpus endometrial carcinoma (1).